CD24 (CD24 molecule)
Diseases named in the same sentence as CD24 in open-access papers (continued):
Sharing a sentence is not in itself a finding about the gene and the disease.
tumor (continued). "Due to the regulation of CD24 on cancer cells, its expression is associated with tumor progress and is used as a stemness marker for cancer." (PMID 40486886, 2025). "Taxanes (paclitaxel/docetaxel) combinations frequently diminish tumor-associated stem-cell populations (CD44+/CD24−), decreasing resistant fractions and improving tumor control." (PMID 41303508, 2025). "In colorectal cancer, CD24 expression was associated with tumor initiation, self-renewal, and differentiation ability to multiple lineages." (PMID 38360723, 2024). "Barkal and colleagues demonstrated that CD24 can play an antiphagocytic role in tumor cells via interaction with Siglec-10 on tumor-associated macrophages." (PMID 38214542, 2024). "In ovarian and breast cancer, tumor-expressed CD24 can interact with Siglec-10 expressed by tumor-associated macrophages to inhibit tumor cell phagocytosis and promote immune evasion." (PMID 39062019, 2024). "CD24, recently identified as highly expressed on tumor cells, interacts with sialic acid binding immunoglobulin-like lectin 10 (Siglec10) on tumor-associated macrophages, thereby evading efferocytosis." (PMID 39660125, 2024). "Due to its diverse post-translational modifications, CD24 has been implicated in tumor development, invasion, and metastasis." (PMID 38881902, 2024). "CD24 has been implicated in tumor growth, invasion, and metastasis, and has been suggested as a potential therapeutic target for cancer treatment." (PMID 38881902, 2024). "Siglec-10, which is expressed in tumor-associated macrophages, binds CD24 in a sialylation-dependent manner and activates cytosolic protein tyrosine phosphatases Src-homology 2 domain (SH2)-containing SHP-1/SHP-2-mediated immune cell inhibition." (PMID 39432076, 2024). "It has been shown that increased CD24 gene expression in the primary tumor was associated with HER2-overexpression, TNBC subtype, high risk of distant metastasis, and short overall and recurrence-free survival." (PMID 38806508, 2024). "CD24 is a small adhesion protein implicated in tumor immune evasion, cancer aggressiveness and remarkably, also into epithelial to mesenchymal transition (EMT)." (PMID 38902710, 2024). "Expression of CD24 on the cell surface and in the cytoplasm was associated with tumor size, histologic grade, lymph node positivity, and poor prognosis." (PMID 38806508, 2024). "The study revealed that increased CD24 promoter methylation and the associated high CD24 gene expression are correlated with biochemical recurrence-free survival, tumor grade, and stage in PC patients." (PMID 39452071, 2024). "Their immunohistochemical analysis of human CRC tissue samples revealed that CD24 expression increases with tumor progression and is strongly associated with the expression of p-ERK1/2 and p-p38 MAPK in the tissue." (PMID 38881902, 2024). "CD24, acting as a signal transducer, is linked to advancing tumours and suppressing the immune system." (PMID 38030594, 2024). "CD24 serves as another “don't eat me” signal, interacting with the inhibitory receptor Siglec‐10 on tumor‐associated macrophages." (PMID 39297408, 2024). "Firstly, the infiltration of T cells (CD3, CD4, CD8, GZMB), tumor-associated macrophages (TAMs, CD11b), B cells (CD24) and NK cells (CD56) within the tumor was assessed by immunohistochemical (IHC) staining." (PMID 38622609, 2024). "The association between CD24 expression and a poor prognosis seems to be attributed to the role of CD24 in regulation of tumor cell migration, invasion, and proliferation." (PMID 38806508, 2024). "Meanwhile, tumour resistance and the risk of inflammation are also issues that need to be addressed in CD24 antibody drug therapy." (PMID 38137380, 2023). "High CD24 expression was significantly associated with worse clinical T stage, lymph node metastasis and tumor size." (PMID 38138858, 2023).
tumor (continued). "As demonstrated, most of the CD44+CD24− BCSCs were located at the invasive edge of the tumor mass, indicating that their presence is associated with enhanced aggressive invasiveness." (PMID 36768876, 2023). "Several oncogenic signaling pathways, including Src/STAT3, EGFR, HER2, MAPK, AKT/mTOR, WNT/-catenin and miRNA-related pathways, have been associated with changes in tumor cell surface CD24 expression." (PMID 37846296, 2023). "Other studies have shown that CD24, which is a cancer stem cell biomarker, is primarily associated with tumor resistance." (PMID 37077416, 2023). "Cluster of differentiation 24 (CD24) is an emerging tumour-associated antigen that is commonly and highly expressed in various tumours." (PMID 38137380, 2023). "In the present review, we aimed to assess the diagnostic utility of the CD44/CD24 combination in tumor development and metastasis in OSCC." (PMID 37664387, 2023). "CD24 expression causes the acquisition of cellular properties associated with tumor proliferation, growth and metastasis, and its potential role in malignancy is yet to be determined." (PMID 38138858, 2023). "An attempt was made to assess the diagnostic utility of CD44/CD24 combination in tumor development, metastasis, and overall survival of patients with OSCC." (PMID 37664387, 2023). "CD24 on the surface of cancer cells binds to Siglec-10 on tumor-associated macrophages (TAMs) to prevent phagocytosis." (PMID 37894750, 2023). "CD24 expression is evident across various human tumor cells, and extensive studies have highlighted the association between its overexpression with tumor formation and progression." (PMID 37894750, 2023). "CD24 is abnormally overexpressed in many tumors compared to normal tissues, and Siglec10 expression is also higher in tumor-associated macrophages." (PMID 37484024, 2023). "A series of findings on CD24 included prominent expression in tumor epithelium, association with pro-tumor immune phenotypes and reduced survival, and functional role in vivo." (PMID 37919766, 2023). "CD24 deficiency increased the oral cavity tumor burden in response to the carcinogen 4-nitroquioline 1-oxide." (PMID 38138858, 2023). "Given the heterogeneity of in post-translational modifications, CD24 has been implicated in tumor growth, invasion, and metastasis, and has been suggested as a potential marker for cancer prognosis and therapy." (PMID 38313430, 2023). "In another study, the possibility of CD24/SIGLEC10 interaction in TNBC under the exposure of tumor-associated macrophages (TAMs) was reported." (PMID 36371461, 2022). "Specifically, CD24 relayed anti-phagocytic signals to phagocytes through its interaction with Siglec-10, a lectin expressed on tumor-associated macrophages (TAMs)." (PMID 35625912, 2022). "Siglec-10 is also expressed by tumour-associated macrophages and can interact with tumour-expressed CD24 to promote immune suppression." (PMID 36077781, 2022). "Downregulated expression of CD86 and upregulated expression of CD24 was observed in tumour-associated Lin− population of most nsECT-treated mice." (PMID 36551739, 2022). "For example, Siglec-10 on tumor-associated macrophages interacted with tumor-expressed CD24, and blockage of both molecules led to a reduction in tumor growth and an increase in survival time." (PMID 36330513, 2022). "Another study investigated the expression of CD133 and CD24 on BC cells and concluded that a CD133posCD24pos phenotype was associated with tumor progression and metastases." (PMID 35628262, 2022). "Surface CD24 expression in tumor cells has been linked with alterations in multiple oncogenic signaling pathways, including Src/STAT3, EGFR, HER2, Ras-like GTPase, MAPK, AKT/mTOR, WNT/β-catenin, and miRNA-related pathways." (PMID 36013184, 2022). "It has been reported that CD24 promotes immune evasion via coupling with sialic acid-binding lg-like lectin 10 (Siglec-10), a inhibitory receptor expressed on tumor-associated macrophages." (PMID 36231025, 2022).
tumor (continued). "The binding of CD24, present on tumor cells, to Siglec-10, expressed on immune cells, causes inhibition of the immune response mediated by the tyrosine phosphatases SHP-1 and SHP-2." (PMID 36432658, 2022). "Another important ligand of CD24 for tumor progression is Siglec 10, which is located, among others, on tumor-associated macrophages." (PMID 36294907, 2022). "Well-characterized stem cell markers CD44 and CD24 have been linked to younger age at diagnosis, higher odds of unfavorable tumor characteristics, including triple-negative status and distant metastasis." (PMID 36590957, 2022). "It was shown before that increased CD24 expression on CCA cells is associated with tumor invasion, disease progression, lymph node metastasis and reduced overall survival." (PMID 35954154, 2022). "The authors demonstrate that tumor-expressed CD24 promotes immune evasion by interacting with the inhibitory receptor sialic acid-binding Ig-like lectin 10 (siglec-10) expressed by tumor-associated macrophages." (PMID 36297672, 2022). "Additional mechanisms that depend upon the expression of CD24 and are implicated in tumor cell extravasation and metastasis include rolling on E-selectin and binding to fibronectin in the extracellular matrix." (PMID 36013184, 2022). "CD24 facilitated immune evasion by interacting with the inhibitory receptor siglec-10 of tumor-associated macrophages." (PMID 36231025, 2022). "Similar results were achieved in the training set of patients following chemotherapy and the patients with a higher frequency of CD44-/CD24- cells had a higher risk to develop distant metastasis beginning at 4 years post tumor resection." (PMID 34318746, 2021). "Elevated levels of CD24 were found to be associated with the spread of the tumor and the formation of metastases." (PMID 34442367, 2021). "Accordingly, we found that combined inhibition of MET and FGFR in a basal B PDX resulted in a decrease in sphere-forming and CD44+CD24−/low populations, indicative of a loss of TICs and reduction in overall tumour burden." (PMID 33772015, 2021). "Differential expression and subcellular localization of CD24 in cancer cells is implicated in tumor initiation, cancer cell proliferation and metastasis, and immune suppression and escape." (PMID 34360932, 2021). "The systematic review included studies evaluating the association of CD24 with tumor initiation, progression, and patient prognosis." (PMID 33806857, 2021). "The higher frequency of CD44-/CD24- tumor cells is associated with delayed distant metastasis and worse DFS in the testing group of patients." (PMID 34318746, 2021). "CD24 interacts with the inhibitory receptor sialic acid binding Ig like lectin 10 (Siglec-10) on tumour-associated macrophages and promotes immune evasion by inhibiting phagocytosis." (PMID 34944851, 2021). "CD24 on tumor cells interacts with siglec-10 on tumor-associated macrophages to promote immune evasion." (PMID 31979120, 2020). "CD24-targeted FIGS can improve the identification of disseminated metastases based on the association of CD24 expression with an advanced stage and the metastatic activity of CD24+ tumor cells, which exhibit fast tumor growth." (PMID 33260974, 2020). "Aside from its interaction with P-selectin, CD24 interacts with sialic-acid-binding Ig-like lectin 10 (Siglec-10), a receptor expressed on tumor-associated macrophages (TAMs)." (PMID 33260974, 2020). "CD24 biomarker expression is associated with aggressive tumours showing increase proliferative activity and invasion." (PMID 32986350, 2020). "Studies of CD24 indicated that its over-expression affected the metastatic tumor spread and was associated with a more aggressive disease in many tumor types, and is used as diagnostic marker in solid tumors." (PMID 31534632, 2019). "In our TMA analysis, CD24 was only associated with tumor stage in the subgroup of cancers of the oral cavity." (PMID 31661833, 2019).
tumor (continued). "Beyond the role of a CSC marker, CD24 is also functionally associated with cell adhesion, contributing to the attachment of tumor cells to fibronectin or collagen during metastasis." (PMID 31277278, 2019). "Primary NB cell lines taken from bone marrow metastases reveal that overexpression of CD24 glycoprotein in cancer cells is associated with accelerated tumor formation and growth." (PMID 31191243, 2019). "Surface markers, such as CD13 and CD24, are functionally implicated in tumor development and progression." (PMID 29888282, 2018). "This is consistent with the reduction of OCT4, NANOG and SOX2 expression, reduction in the BCSC population by loss of the ALDH1 and CD44+/CD24– population, the deformation of mammospheres, and the strong reduction in animal tumor volume and tumor weight." (PMID 30542507, 2018). "High levels of CD24 expression and its association with quiescence, chemo-resistance, tumor initiation, and metastatis have been reported in several cancers." (PMID 30121075, 2018). "High-power histology analyses revealed that in addition to the differences in tumor sizes and incidences, Cd24 deficiency increased malignancy of liver tumors." (PMID 29423273, 2018). "Since it has been shown that a specific subpopulation of aggressive tumor cells is associated with stem cell-like properties, we assessed CD24, CD29, and CD44 expression in HSC-3 cells by flow cytometry." (PMID 30029671, 2018). "The effect of GCB, TQ and their combination against tumor associated stem cell clone (CD44+/CD24−) was assessed using flow cytometry." (PMID 30076320, 2018). "How the downstream signaling of CD24 causes the change in sensitivity of tumor cells to taxane versus anthracylines remains to be answered." (PMID 28418843, 2017). "Given that CD44+/CD24- cells in TNBC have been shown to possess tumor-initiating properties and to be associated with resistance to chemotherapy, we analyzed the two surface markers in both docetaxel sensitive and resistant TNBC cell lines." (PMID 29190901, 2017). "The loss of CD24 function has also been related with induction of apoptosis and decreased rates of cell proliferation in several tumor cell lines." (PMID 28611669, 2017). "In the present study, we evaluated the potential role of CD24 on tumor angiogenesis in CRC and the underlying molecular mechanisms." (PMID 27494878, 2016). "The effect of CD24 deficiency on the tumor burden was assessed by quantifying the mass of the tumor-bearing mammary glands." (PMID 26978528, 2016). "Our finding showed that BRCA1 knockdown induced the expansion of the CD49f+EpCAM+ subpopulation in the CD44+CD24– cell subset of MCF10DCIS tumor cells, confirming the relationship between BRCA1 deficiency and luminal progenitors." (PMID 27556296, 2016). "If CD24 functionally contributes to the stemness properties of CSCs in these models, then loss of CD24 would be expected to have pronounced effects on tumor initiation and growth." (PMID 26978528, 2016). "In line with loss-of-function assay, gain of CD24 function imparted more colony formation capacity in tumor sphere, soft agar assay, and therapeutic resistance in comparison with CD44 overexpression." (PMID 27521216, 2016). "CD24 expression has long been correlated with pathologies associated with tumor cell migration and invasion." (PMID 26440795, 2015). "Recent studies indicate that CD24 expression is associated with tumor progression and poorer survival rates." (PMID 26578846, 2015). "In univariate analyses for LA tumors, a poorer DMFS over the first 5 years was associated with young age (≤40 years), large tumor size (20 mm), higher mSBR (grade 2 + 3 versus 1), vascular invasion, axillary nodal involvement, CD24 and Trio phenotypes." (PMID 26405647, 2015).
tumor (continued). "In the current study, we demonstrate that CD24 level in peripheral blood leukocytes (PBLs) can be used as a potential marker for the detection of CR neoplasia and examine the possible implications of CD24 genetic variants in the genetic predisposition to CRC." (PMID 26078485, 2015). "The underlying biological mechanisms of CD24 promoted tumor progression are still incompletely characterized, although a growing number of studies have contributed to our comprehension." (PMID 26578846, 2015). "Consistent with our data, in other tumor cell-lines derived from breast and of other tissues the CD24+/CD44+ cell subpopulation has previously been associated with a CSC-enriched phenotype due to increased tumorigenicity in mice." (PMID 26020648, 2015). "CD24−/CD44+ tumor cells or ALDH1-positive tumor cells were significantly associated with poor survival in a recent meta-analysis, although ALDH1 expression alone does not significantly predict outcomes." (PMID 26405647, 2015). "The loss of sphere-forming capacity and efficacy of tumour formation for CD24- MM cells can be linked to their loss of several other stemness markers, including CD47, EpCAM and OCT4, as shown for the tumour tissue." (PMID 25932953, 2015). "Herein, we show that CD24 expression in PBLs can serve as a potential promising screening tool to select which healthy subjects are in fact at risk of having CR neoplasia and need to undergo screening colonoscopy." (PMID 26078485, 2015). "The protein expression of RRM2 was also positively and significantly associated with CD44+/CD24-/low, a tumor stem/progenitor cell biomarker." (PMID 25213022, 2014). "CD24 expression causes the acquisition of multiple cellular properties associated with tumor growth and metastasis." (PMID 24612587, 2014). "The association between CD24 expression and tumor recurrence was observed in each tumor category [stages Ta and T1, low- (G1) and high-grades (G2–G3)]." (PMID 23946784, 2013). "In the present study, the differential expression of genes associated with cancer metastasis in CD24+ and CD24− cells was investigated using the Human Tumor Metastasis RT2 ProfilerTM PCR array (Qiagen, Valencia, CA, USA)." (PMID 24179538, 2013). "The expression of CD24 is associated with tumor development and plays a critical role in various cancer metastases." (PMID 23799994, 2013). "Using a human tumor metastasis PCR array, it was observed that numerous tumor-associated genes were upregulated in the CD24+ cells, including CXC chemokine receptor type 4 (CXCR4)." (PMID 24179538, 2013). "In the present study, the PCR array system was used to focus on human tumor metastasis and identify genes associated with metastasis that are affected by CD24 expression." (PMID 24179538, 2013). "The positive association between CD24 expression and tumor recurrence was observed in each tumor category (stages Ta and T1, low and high grade)." (PMID 23946784, 2013). "CD44 expression was linked with low-grade tumours (P=0.02), while there was a trend for CD24 to associate with advanced T-stage (P=0.08)." (PMID 22333601, 2012). "The association between the proportions of CD44+/CD24- tumor cells and the clinico-pathological features of these patients was evaluated." (PMID 22762532, 2012). "Analysis of CRC tissues with immunohistochemistry staining showed that the expression of CD24 and Lyn was positively correlated and associated with tumor stage and lymph node and distant metastasis." (PMID 22731636, 2012). "We also found that tumours enriched for the CD44+CD24-/low phenotype were associated with the basal-like subtype and with negative lymph node status." (PMID 22112299, 2011). "Since the discovery of the high capacity of generating new tumor cells by mammary CD44+CD24-/low cells, this phenotype are associated with worse survival and aggressive behavior." (PMID 21824412, 2011).